GPX4 (glutathione peroxidase 4)
Diseases named in the same sentence as GPX4 in open-access papers (continued):
Sharing a sentence is not in itself a finding about the gene and the disease.
cancer (continued). "To further validate the potential of our prediction, we examined the correlation between all genes in the CCLE dataset to the FIN AUCs (taken from the CTRP drug sensitivity dataset) in pan-cancer and to GPX4 dependency score (taken from Achilles dataset, Broad)." (PMID 39310772, 2024). "Similarly, high expression of GPX4 and FSP1 in cancer cells is presumed to reduce oxidative stress caused by cell proliferation and exposure to anticancer drugs, thereby promoting cancer cell survival and leading to a poor prognosis." (PMID 39594843, 2024). "Co-induction of ferroptosis and cuproptosis by targeting the glutathione-GPX4 system may be a more effective strategy to induce cell death in cancers that are currently resistant to various types of cell death." (PMID 39273151, 2024). "Moreover, in CC, the small molecule drug honokiol can restrain cancer cell growth by boosting GPX4 enzyme activity to enhance ferroptosis." (PMID 39548421, 2024). "Similarly, treatment with HDL NPs, which depletes cancer cells of GPx4, sensitized Pt‐R cancer cells to carboplatin." (PMID 38263873, 2024). "Notably, cancer is a primary focus due to the ubiquitous expression of Gpx4, which is crucial for cancer cell survival." (PMID 39058145, 2024). "However, mesenchymal cancer cells, often resistant to various treatments, are highly sensitive to ferroptosis by targeting GPX4." (PMID 38378601, 2024). "Indeed, high levels of GSH are observed in the majority of tumors, contributing to cancer progression and treatment resistance in part by preventing glutathione peroxidase 4–dependent (GPX4-dependent) ferroptosis, an iron-dependent programmed cell death." (PMID 38441967, 2024). "Notably, GPX4 inhibition can selectively induce ferroptosis in cancer cells while sparing normal cells that exhibit lower basal lipid peroxidation and stronger antioxidant defences." (PMID 39881871, 2024). "Similarly, miR-15a-3p, miR-1287-5p, and miR-324-3p exert analogous effects in cancer by directly targeting GPX4 to positively modulate ferroptosis." (PMID 39036600, 2024). "Last but not least, IDH1-mutated cancer cells, which have increased levels of the oncometabolite 2-hydroxyglutarate, also become vulnerable to GPX4 inhibition-induced ferroptosis." (PMID 38908072, 2024). "However, this protective mechanism also enables cancer cells to survive under oxidative stress, which makes GPx4 a potential druggable target in cancer therapy." (PMID 39594547, 2024). "In 2014, they reported GPX4 as an important inhibitor to ferroptotic cancer cell death." (PMID 39881868, 2024). "Thus, inhibition of ferroptosis protection systems—for example, by GPX4 inhibitors—is particularly effective in highly aggressive mesenchymal-type cancer cells." (PMID 39009641, 2024). "This modulation renders the cancer cells more prone to ferroptosis in a GPX4-dependent manner." (PMID 38217037, 2024). "GPX4 has been identified as the target for cancer therapy, especially for drug-resistant cancers." (PMID 38247539, 2024). "For example, cancer cells with altered iron metabolism and higher ROS production are more prone to ferroptosis, while cells with stronger antioxidant defenses, such as those expressing high levels of GPX4, are more resistant." (PMID 39335181, 2024). "However, some cancer cells can survive even after GPX4 inactivation, suggesting the existence of alternative mechanisms that confer resistance to ferroptosis." (PMID 39624080, 2024). "GCH1 expression level in cancer cell lines stratified susceptibility to ferroptosis, demonstrating a peculiar mechanism of ferroptosis protection that is not dependent from the GPX4/GSH system." (PMID 37132605, 2024).
cancer (continued). "Ferroptosis is a new type of non-apoptotic programmed cell death caused by the loss of GPX4 activity and subsequent accumulation of lipid-based ROS and is considered an effective target for cancer treatment." (PMID 38756246, 2024). "We reasoned that the induced GPX4 expression after NTP + RSL3 treatment might represent an adaptive response wherein cancer cells tried to recover cell survival in response to excessive ROS." (PMID 38347507, 2024). "Since the discovery of GPX4-centered ferroptosis mechanisms in 2014, additional pathways, both GPX4-dependent and independent, have been identified, offering a broader understanding of ferroptosis regulation and its therapeutic potential in cancer." (PMID 39335181, 2024). "In addition, the expression of AIFM2 positively correlates with resistance to GPX4 inhibitors in cancer cell lines, suggesting that FSP1 inhibitors have potential utility as an alternative therapeutic strategy." (PMID 37371948, 2023). "The expression pattern of GPX4 also differs depending on the cancer type." (PMID 36576648, 2023). "However, recent studies have demonstrated that long GPX4 also plays an important role in ferroptosis protection in doxorubicin-induced cardiomyopathy and in cancer models under certain conditions, as described in the following Section 3.3." (PMID 37190037, 2023). "Moreover, the inhibition of SLC7A11 or GPX4 has been shown to enhance IR sensitivity in radioresistant cancer cells and xenografts." (PMID 37488128, 2023). "Elevated GPX4 levels are frequently observed in many types of cancer, implying that it may be protumorigenic." (PMID 37198609, 2023). "Also, emerging evidence has demonstrated the interplay between the mTOR and GPX4 signals, modulating autophagy-dependent ferroptosis in several cancer cells." (PMID 38097554, 2023). "GPX4 is involved in the induction of ferroptosis in cancer cells." (PMID 38023171, 2023). "Interestingly, several studies describe that the inactivation of GPx4 by the inhibitor of ferroptosis leads to oxidative destruction of the cancer cell via ferroptosis." (PMID 38202704, 2023). "Thus, SLC7A11 and GPX4 are important ferroptosis regulators as well as potential targets for cancer therapy." (PMID 37834062, 2023). "Interestingly, shSETD2 alone was able to increase GPX4 protein expression, which is possible that it was compensatorily to balance the redox homeostasis of the cancer cells." (PMID 37604811, 2023). "Moreover, it has been previously shown that GPX4 overexpression in cancer cells inhibits RSL3-mediated ferroptosis, whereas GPX4 deletion increases susceptibility to ferroptosis." (PMID 36792890, 2023). "Thus, inhibiting GPX4 to induce ferroptosis is considered to be a useful means of taking advantage of this “Achilles heel” to inhibit cancer progression." (PMID 37325669, 2023). "Furthermore, inhibiting HSF1 specifically can reverse the ferroptosis resistance generated by GPX4 suppression and greatly improve the in vitro sensitivity of resistant cancer cells and tumors to ferroptosis." (PMID 37868994, 2023). "Based on the results of our wide research in PubMed, Web of Science, and FerrDB databases, This review focus on the structure, expression regulation, and function of GPX4 in ferroptosis and the relationship between GPX4 and its influence on ferroptosis in cancer therapy." (PMID 36675129, 2023). "GPX4 inhibits ferroptosis in cancer cells, including EMT, that are resistant to therapy." (PMID 37598126, 2023). "Furthermore, FSP1 inhibitors have demonstrated the ability to overcome resistance to ferroptosis in cancer cells resistant to GPX4 inhibitors." (PMID 37371948, 2023). "Considered with the current study results, simultaneous FSP1 and GPX4 regulation may represent a new target for cancer therapy via induction of ferroptosis." (PMID 36576648, 2023). "GPX4 inhibition has been proposed as a therapeutic strategy to induce ferroptosis and treat cancer." (PMID 37337630, 2023).
cancer (continued). "Therefore, the upregulation of SLC1A5 inhibits the production of MDA and upregulates GPX4 to reduce oxidative stress-related damage, thereby accelerating cell proliferation and promoting malignant tumor progression." (PMID 37566748, 2023). "Cancer cells with a high mesenchymal state have higher clinical stages and are selectively sensitive to ferroptosis, which suggests that they are sensitive to GPX4 inhibition." (PMID 36675129, 2023). "In addition, suppression of GPX4 is an important strategy to overcome the resistance of cancer to chemotherapy." (PMID 37408372, 2023). "While studies across various cancers have highlighted the efficacy of ferroptosis induction, particularly by inhibiting GPX4 and AIFM2, in eliminating apoptosis-resistant cancer cells, the exploration of ferroptosis in the context of AML remains relatively limited." (PMID 38032290, 2023). "However, the regulatory mechanism of GPX4 during cancer cell ferroptosis remains to be further investigated." (PMID 37248295, 2023). "Recent reports have demonstrated that in a high-mesenchymal cell state, cancer cells might be more dependent on GPX4." (PMID 37046995, 2023). "Indeed, sodium selenite was shown to induce regulated cell death by disturbing a number of the most fundamental elements of ferroptosis, including SLC7A11, GSH and GPx4, which inevitably led to ROS generation and lipid peroxidation in human cancer cells." (PMID 36835045, 2023). "While the GPX4/GSH system protects most types of cells from ferroptosis, recent studies suggest that chemoresistant cancer cells with mesenchymal characteristics or drug-tolerant cancer cells are particularly susceptible to ferroptosis." (PMID 37714840, 2023). "Collectively, these data suggested that silencing PRMT3 could inhibit the resistance of cancer cells to ferroptosis by suppressing GPX4 expression in EC." (PMID 37973560, 2023). "Therefore, in this study, we performed pan-cancer analysis and characterized the immune infiltration patterns with respect to GPX4 expression." (PMID 38065948, 2023). "Targeted regulation of GPX4 is promising as a novel approach to cancer therapy." (PMID 38023171, 2023). "In addition, we collected clinical specimens and detected differences in GPX4 expression between cancer and paracancerous tissues." (PMID 36626251, 2023). "Many chemotherapeutic drugs have been shown to induce ferroptosis in cancer cells by pharmacologically regulating or genetic pathways and eliminate the treatment resistance by targeting lipid metabolism, iron metabolism, and canonical GPX4-regulated pathways." (PMID 37996827, 2023). "Taken together, our findings indicate that GPX4 may be a novel modulator of cancer immunotherapy via activating the cGAS-STING signaling pathway in COAD." (PMID 38065948, 2023). "In all, our study demonstrated that m6A and m5C modification of GPX4 may be a promising target for cancer immunotherapy via activating the cGAS-STING signaling pathway in COAD." (PMID 38065948, 2023). "High-grade or drug-resistant cancer cells are also selectively sensitive to GPX4 inhibitors." (PMID 37046995, 2023). "Conversely, it may also sensitize cancer cells that were previously resistant to RSL3-induced ferroptosis by promoting ferroptosis in GPX4-KO cancer cells that overexpress FSP1." (PMID 37576601, 2023). "We also found that inhibiting NRF2 with ML385 inhibited the viability of various AML cell lines, suggesting that NRF2 and GPX4 could represent promising targets for the treatment of AML cancer cells." (PMID 37198609, 2023). "Therefore, to achieve effective ferroptosis in cancer cells, it is important to inactivate GPX4 or deplete GSH while delivering iron." (PMID 37563614, 2023). "Importantly, therapy-resistant or -persistent solid cancer cells with a mesenchymal gene signature exhibit vulnerability to GPX4 inhibition, which suggests that targeting GPX4 has therapeutic potential in certain intractable phases or types of cancers." (PMID 37190037, 2023).
cancer (continued). "Notably, cancer cells exhibit low levels of glutathione peroxidase 4 (GPX4) and inhibition of DHODH hinders respiration, boosts glycolysis and enhances GLUT4 translocation to the plasma membrane." (PMID 38577257, 2023). "In addition, many experimental compounds targeting system Xc−, GPX4, and Nrf2 have been used to induce ferroptosis against cancer development." (PMID 37065473, 2023). "GPX1 and GPX4 inhibitors have thus shown promise as anti-cancer agents, and targeting other GPX isoforms may prove equally beneficial." (PMID 37244126, 2023). "GPX4 seems to be particularly relevant in cancer development." (PMID 37554285, 2023). "It was reported that RSL3 treatment to BJeLR and HT1080, the two cancer cell lines in which ferroptosis was originally identified, accompanied reduction in GPx4 protein abundance with unknown mechanisms." (PMID 36595221, 2023). "Thus, inducing ferroptosis in cancer cells via inactivation or degradation of GPX4 is being intensely pursued as a novel cancer treatment strategy." (PMID 37564206, 2023). "For example, one of the promising anti-cancer therapeutic strategies via ferroptosis induction is the inhibition of glutathione peroxidase 4 (GPX4), an enzyme catalyzing the peroxide reduction at the expense of GSH and therefore preventing cells from ferroptosis." (PMID 37823053, 2023). "This may be because GPX4 is necessary or has a more functional role in the GPX4 overexpressing cancer cell, making the cells sensitive to RSL3." (PMID 37258589, 2023). "Besides, potential molecular mechanisms involved in ferroptosis were observed in many experimental cancer models, including inactivation of GPX4, up‐regulation of FACL4." (PMID 35855531, 2023). "Due to the high expression level of the GSH-dependent enzyme GPX4 in various cancers and its function in inhibiting the generation of lipid ROS, targeting GPX4 might be an efficient method to induce ferroptosis in cancer cells." (PMID 36926345, 2023). "In brief, GPX4 can prevent cancer cells from ferroptosis by countering lipid peroxidation." (PMID 37065473, 2023). "In the cellular ferroptosis defense mechanism, GPX4 and SLC7A11 indeed play important roles, especially in malignant tumors where aberrant expression or function of GPX4 and SLC7A11 often accompanies and affects the susceptibility of cancer cells to ferroptosis." (PMID 37723588, 2023). "Additionally, when FSP1 inhibitors are combined with GPX4 inhibitors, a synergistic effect is observed in inducing ferroptosis in cancer cells." (PMID 37371948, 2023). "Several studies have reported the role of CAP in inducing cancer cell ferroptosis, consolidating our hypothesis on the regulatory role of β-catenin on GPX4 through forming complexes with TCF." (PMID 37671945, 2023). "However, the metabolic vulnerability of tumors provides therapy opportunities, and drug-tolerant persistent cancer cells rely on GPX4 activity to resist treatment." (PMID 37325669, 2023). "In particular, temporally resolved results showed that ferroptotic phenotypes were rapidly induced by bringing GPX4 factor to the proximity of peroxisomes, and this approach may serve as a valuable mean to induce cancer cell death." (PMID 36964170, 2023). "Similarly, in breast cancer, expression of SLC7A11 and GPX4 were elevated, which were found to play a critical role in promoting cancer cell survival and resistance to ferroptosis." (PMID 37266741, 2023). "This dependency exposes a cancer cell vulnerability, in which inhibition of GPX4 either directly or indirectly with erastin (a compound which inhibits the import of cystine, leading to GSH depletion and inactivation of GPX4) results in excessive lipid peroxidation causing cancer cell death." (PMID 36675307, 2023). "GCDs induced the ferroptosis of cancer cells, as shown by decreased GPX-4 and increased COX-2." (PMID 36969027, 2023).
cancer (continued). "GPX4 was positively associated with TMB and MSI in several cancers, indicating that it may reflect potential benefit from antitumor immunotherapy in these cancers." (PMID 38065948, 2023). "Since GPX4 inhibition may be toxic to various normal tissues, including the heart, kidneys, and liver, how to deliver drugs specifically to cancer tissues remains a challenge." (PMID 37714840, 2023). "It is suggested that the GPX4 inhibitor triggers ferroptosis in cancers." (PMID 37458878, 2023). "However, in some cancer cell lines, suppression of GPX-4 cannot trigger ferroptosis, suggesting that alternative ferroptosis-resistant modulators exist in cancer cells." (PMID 36986483, 2023). "Recently, targeting GPx4 remains an active area of drug development in cancer therapy." (PMID 36923926, 2023). "Since then, research has been conducted using various ferroptosis inducers, including erastin as an SLC7A inhibitor and RSL3 as a GPX4 inhibitor, to explore the anticancer effects of these compounds regardless of RAS mutation and to overcome therapy resistance in various cancer cells." (PMID 37258589, 2023). "Cancer cells with low expression of the core system xc–/GPX4 pathway are more likely to depend on the CoQ10 or other antioxidant systems, making them vulnerable to inhibiting GPX4-independent ferroptosis defense systems." (PMID 37371948, 2023). "GSH depletion promotes the ferroptosis of cancer cells by reducing GPX4 activity." (PMID 37714846, 2023). "Regulating GPX4 activity also affects ferroptosis and radiosensitivity of cancers." (PMID 37714846, 2023). "Therefore, given its unique mechanism, the role of GPX4 in ferroptosis has recently become a new and popular research field, on the basis of ferroptosis in cancer therapy." (PMID 36675129, 2023). "Taken together, activators of the NRF2/HO‐1 axis that additionally reduce GPX4 expression have promising cancer cell selectivity and, when given as combination therapy with conventional drugs, might even protect normal cells." (PMID 36658724, 2023). "Moreover, the inhibition of cancer cell proliferation was studied through down-regulation of GPX4 alone with AuNF probes or through the synergistic effect of erastin and AuNF probes." (PMID 36551145, 2022). "Second, ferroptosis prevented by GPX4 might be one of the mechanisms that explain the relative immortal nature of cancer cells that contributed to poor prognosis in patients with GPX4-positive NSCLC in this study." (PMID 36443446, 2022). "The GPx4 was discovered in 1982 as a cytosolic “peroxidation inhibiting protein” and today represents a specific target for new pharmacological treatments aiming at activating cell death in cancer." (PMID 35163250, 2022). "However, GPX4 inhibitors have different responses in different cancer cells, suggesting that other mechanisms regulate ferroptosis in different cells." (PMID 36387147, 2022). "Inhibiting GPX4 by XCT suppression has been a practical way to induce cancer cell ferroptosis." (PMID 36397015, 2022). "For example, circDTL reduced the ferroptosis of cancer cells via the miR-1287-5p/GPX4 pathway." (PMID 35342359, 2022). "Therefore, the induction of ferroptosis in cancer cells by inhibiting GPX4 is currently promising as a therapeutic strategy for some cancers." (PMID 36230941, 2022). "GPX4-deficient cancer cells can be efficiently eliminated by the FSP-specific inhibitor iFSP1, while in GPX4-expressing cancer cells, iFSP1 cooperates with RSL3 to induce cancer cell ferroptosis." (PMID 36425577, 2022). "Compared with normal cells, though, cancer cells are more sensitive to GPX4 inhibition." (PMID 36317423, 2022).